TNF (tumor necrosis factor)
Diseases named in the same sentence as TNF in open-access papers (continued):
Sharing a sentence is not in itself a finding about the gene and the disease.
diabetes (continued). "In fact, diabetes is considered an inflammatory disease that is characterized by increases in oxidative stress (e.g., the oxidation of glucose) and advanced glycation end-products (AGE), which induce the up-regulation of many inflammatory cytokines, such as MCP-1, TNF-α, IL-1, and IL-6." (PMID 21984919, 2011). "Likewise, it has been reported that patients with T2DM and COVID-19 had a higher count of white blood cells, neutrophils, and proinflammatory cytokines (such as IL-6 and TNF-α), suggesting an increased inflammatory response compared to patients without diabetes." (PMID 40406515, 2025). "Although the ST extract did not induce gene expression of TNF-α in MIN6 cells, these data suggest that the ST extract does have pro-inflammatory activity, which may be relevant for the macrophage-pancreas interactions that underlie progression of diabetes." (PMID 40308759, 2025). "For instance, chronic non-infectious diseases such as diabetes mellitus, coronary artery disease, hypertension, and chronic obstructive pulmonary disease are known to lead to increased levels of cytokines (e.g., interleukin-2, tumor necrosis factor), which can induce depressive symptoms." (PMID 40110545, 2025). "However, in patients undergoing renal replacement therapy (either hemodialysis or continuous peritoneal dialysis), irrespective of the presence of diabetes mellitus, the serum levels of inflammatory markers (i.e., IL-6, IL beta, IL 10, or TNF alpha) are heterogenous." (PMID 38921685, 2024). "TNF-α and IL-1β have often been mentioned as playing a key role in both type 1 and type 2 diabetes, and IFNγ is another proinflammatory factor that is critical to the pathogenesis of both types of diabetes, but has not been extensively studied in diabetic retinopathy." (PMID 37670018, 2023). "Interestingly, ZW inhibited diabetes-induced anxiety and depression by minimizing the neuroinflammatory response by decreasing NfκB, IL-1β, and IL6 mRNA levels and the number of TNF-α- and GFAP-immunostained neurons and serum level of TNF-α and CRP because of its antioxidant power." (PMID 38105928, 2023). "However, the animals in our cardiometabolic disease onset model did not have diabetes, which may explain why higher TNF-α levels did not modify gene expression." (PMID 37585913, 2023). "In the current revascularized CAD cohort with OSA, TNF-α-308G/A gene polymorphism was significantly correlated with the change in circulating TNF-α levels from baseline in response to 12 months of CPAP treatment, independent of age, sex, BMI, baseline AHI, ESS, and diabetes." (PMID 37629366, 2023). "Therefore, the significantly reduced cytokines (IL-1α, IL-6 and TNFα) levels in the hippocampus of the DB and DAV groups, contrary to previous reported increases, may suggest a compromised immune response and prolonged diabetes." (PMID 35453953, 2022). "Moreover, GapmeR-mediated knockdown of human DNM3OS in human THP1 monocytes inhibited inflammatory genes (IL6, TNF, and ITGAX) and phagocytosis similar to actions of the mouse ortholog, suggesting DNM3OS upregulation in humans likely contributes to enhanced inflammation in diabetes." (PMID 34234740, 2021). "While there have been no previous studies comparing TNF-α secretion in DF from patients with or without diabetes, we hypothesised that there may be significant differences in the secretion and/or response to TNF-α by DF derived from T2DM skin that may impact on wound healing." (PMID 33446687, 2021). "Moreover, in T1DM patients, higher adiponectin and TNF-α values were significantly correlated with younger ages at inclusion and at the onset of diabetes, and they also showed significant negative correlations with age at the onset of autoimmune diseases and HDL-cholesterol levels." (PMID 33202729, 2020).
diabetes (continued). "Considering the contributions of persistent elevation of TNF-α to hyperglycemia, this preliminary finding might provide a novel dietary avenue for individuals with isolated IFG to alleviate hyperglycemia and delay the onset of diabetes, which might also be of immense clinical value." (PMID 32509152, 2020). "In this study, heat-killed S. thermophilus may also affect diabetes through the BMID axis by increasing the abundance of beneficial bacteria, protecting the intestinal epithelial barrier, and suppressing IL-6, LPS, and TNF-α secretion, and the end result is moderation of insulin tolerance." (PMID 31223540, 2019). "In guinea pigs, pro-inflammatory cytokines such as tumor necrosis factor (TNF)-alpha and interleukin 6 (IL-6) produced during inflammation promote the release of free fatty acids from adipose tissue which may reduce insulin action on skeletal muscles resulting in dysglycaemia and diabetes mellitus." (PMID 28137307, 2017). "Our results indicate that diabetes acts through other mechanisms to promote atherosclerosis, and further suggest that macrophage production of IL-6 or TNF-α might not explain diabetes-accelerated atherogenesis since these cytokines were significantly altered by EP4-deficiency." (PMID 27351842, 2016). "However, later in the research we have determined that it was not for the duration of diabetes but for the tumor necrosis factor alpha (TNF-α) that the highest discriminant value was demonstrated in predicting the development of microangiopathy in youth with T1DM." (PMID 24688225, 2014). "Interestingly, in those with both diabetes and LF, the pro-inflammatory cytokines - TNF-α, IL-6 and GM-CSF were reduced, compared to those without LF, suggesting that LF-mediated reduction of pro-inflammatory cytokines negatively influences the development of IR." (PMID 20559443, 2010). "There is reduction in pro-inflammatory markers like hsCRP, IL-6, IL-1β, TNF-α, and IFN-γ in patients with diabetes and in vitro models without diabetes, while there is a change in polarity from M1 to M2 macrophages when treated with SGLT2i." (PMID 40868177, 2025). "IGF-1 demonstrated negative correlations with age, duration of diabetes, fasting glucose, HbA1c, total cholesterol, triglycerides, low-density lipoprotein cholesterol (LDL-C), fasting insulin, HOMA-IR, and TNF-α." (PMID 41393761, 2025). "Compared with normal mice without diabetes, we found 1,059 DEGs in the cardiac RNA of db/db mice, and some enriched in four inflammatory pathways, namely, the PPAR, NF-kappa B, TNF, and IL-17 signaling pathways." (PMID 39611812, 2025). "In contrast, in Subtype C, the TNF pathway exclusively mediated communication from Non-Classical Monocytes to other monocyte and T-cell subtypes (as receptors), suggesting its involvement in promoting inflammatory processes that may exacerbate diabetes complications." (PMID 39877357, 2024). "In diabetes mellitus, the isoform PAR-4 rather than PAR-1 is activated through a PKCδ/NF-κB-dependent pathway, which enhances VSMCs migration and TNF-α expression." (PMID 37974282, 2023). "Thus, our aim was to explore whether individuals with diabetes and normal or prolonged segmental gastrointestinal transit times exhibit differences in the systemic levels of the inflammatory cytokines (interleukin (IL)-6, IL-8, IL-10, interferon (IFN)-γ, and tumour necrosis factor (TNF)-α)." (PMID 37189645, 2023). "As a previous study demonstrated, in STZ-induced diabetic rats, the proinflammation proteins TNF-α and CXCR4 were both enhanced at the initial phase (2 weeks) of diabetes in the DRG but did not change in the spinal cord dorsal horn." (PMID 35799894, 2022). "Analysis of the role of diabetes in CABG patients shows that diabetic patients had a significantly higher release of IL-8 and TNFα compared to non-diabetic patients." (PMID 35935655, 2022).
diabetes (continued). "TGF-β and IL18 in people without diabetes and TNF-α and IL2RA in people with diabetes were independent predictors of SRA1 expression." (PMID 34685582, 2021). "While expression of the TGR5 receptor did not change with IF or diabetes, IF reduced TNF-α (Tumor necrosis factor alpha) mRNA, a downstream target of TGR5 activation." (PMID 33669313, 2021). "We observed that inflammatory markers (TNF-α and IL-18) protein expression was positively correlated with SRA1 protein expression in individuals without diabetes." (PMID 34685582, 2021). "TNF-α also predicted SRA1 adipose expression in both NW and obese populations, regardless of diabetes status." (PMID 34685582, 2021). "One clinical trial indicated that eight weeks of probiotic yogurt treatment significantly reduced the TNFα level, but while levels of IL-6 and CRP were also decreased, these findings were not statistically significant among those with diabetes." (PMID 33557067, 2021). "The immune-related genes (NCR3 and TNF) and immune cells (NK cells) may play a vital regulatory role in the occurrence and development of T1DM, which possibly provide new ideas and potential targets for the immunotherapy of diabetes mellitus (DM)." (PMID 34311758, 2021). "According to a recent meta-analysis, saffron is effective in improving the levels of inflammatory markers such as TNF-α, IL-6 and CRP when administered at specific doses (≤30 mg/day) in young adults (<50 years old) lacking a diabetes diagnosis." (PMID 34959826, 2021). "Non-diabetic individuals had lower MCP-1 and TNF-alpha levels than diabetics, and the MCP-1 levels were also significantly lower in non-diabetics than people with diabetes after surgery." (PMID 33865458, 2021). "Neither the expression of the ICAM-1, TNFα, nor MCP-1 was affected by either diabetes or Cmpd17b treatment." (PMID 32085666, 2020). "At 24 h, 48 h and 72 h post-infection, the levels of IL-1Ra, IL-6, IL-8, IL-10, IL-12p40, TNF-α, MCP-1, and MIP-1b were still low in ESRD without diabetes group than in the control group." (PMID 31875015, 2019). "However, PGRN but not TNFα was weakly associated with increased ACR (Micro) even after adjustment for either TNFR, suggesting that measurement of PGRN may be related to development of early renal injury in patients with diabetes." (PMID 30333553, 2018). "Together, these observations suggest that reduction in IFN-γ and TNF-α expressing pro-diabetogenic CD4+ and CD8+ T cells, without any enhanced contribution from Treg cells, likely accounts for attenuation of diabetes in pCD11c-Aire mice." (PMID 28966617, 2017). "Previous diabetes induction in vivo and high glucose concentrations in vitro significantly downregulated SIRT1 amounts as detected in Western blot assays, whereas TNF-α (30 ng/ml) stimulation failed to induce significant changes." (PMID 23734259, 2013). "In our study, we found that the levels of TNF-alpha and IL-6 in NAC-treated diabetic rats were significantly lower than that in the untreated diabetes, but still slightly higher than that in nondiabetic rats." (PMID 23853776, 2013). "Lack of TNFα increased higher basal VCAM-1 protein and sVCAM-1, but failed to up-regulate IL-6 and IL-1β mRNA and VCAM-1 protein in response to diabetes." (PMID 20856927, 2010). "Through immunofluorescence, TNF-α was colocalized with Iba-1 but not with GFAP, indicating that microglia are the main cell type producing TNF-α; at least during the 2-weeks of diabetes." (PMID 21042558, 2010). "FF treatment successfully prevented the diabetes-induced increase in aortic MPO levels; however it failed to affect the increased serum TNF-α levels." (PMID 21234421, 2010). "Notably, although not assessing inflammation in patients with diabetes, in a systematic review assessing the role of GLP‐1RAs in patients with HS, GLP‐1RAs were found to reduce TNF‐α, IL‐17, and NF‐κB levels in patients." (PMID 40888511, 2025).
diabetes (continued). "In the group with diabetes, it was verified positive correlations between IL-10 and IL-6 or IFN-γ and a negative correlation between IL-6 and PMP, at T0; in contrast, in the T1, negative correlations were found between TNF-α and IL-10 or PMP." (PMID 39253540, 2024). "Besides, at T0, it was evidenced positive correlations both between circulating TNF-α and IL-6, and IL-10 and EMP, as well as a negative correlation between IL-10 and PMP in the group with diabetes." (PMID 39253540, 2024). "TNF-α also predicted SRA1 in both NW and obese people regardless of the diabetes status." (PMID 34685582, 2021). "In contrast, MIF expression was significantly reduced in T2DM-DF compared to ND-DF (58.7 ± 12.3 vs 280.4 ± 126.2% GAPDH; P = 0.0016 for effect of diabetes, two-way ANOVA, n = 4), while TNF-α had no modulatory effect in either (P = 0.7303 for effect of TNF-α, two-way ANOVA, n = 4)." (PMID 33446687, 2021). "The authors hypothesise that whole saliva soluble-urokinase-type plasminogen-activator receptor (suPAR) and tumor necrosis factor-alpha (TNF-α) levels are higher in patients with poorly-controlled than well-controlled type-2 diabetes mellitus (DM) and non-diabetic controls." (PMID 34585873, 2021). "Besides, TGF-β and IL18 independently predicted the SRA1 expression in non-diabetics as well as in the total (diabetic and non-diabetic) study population, while TNF-α and IL-2RA were the independent predictors of SRA1 only in people with diabetes." (PMID 34685582, 2021). "One study in type 2 diabetes mellitus (T2DM) patients demonstrated that Propolis at a dose of 1000 mg/ day administration for 3 months, significantly decreased hs-CRP and TNF-α levels but had no significantly difference seen for the serum IL-1β and IL-6 levels." (PMID 32817750, 2020). "And finally, the signaling circuit TNF signaling pathway:CREB3, which neither presents a different activity in the comparison nor the functions triggered are likely to be directly related with diabetes." (PMID 31831811, 2019). "At 6 h post-infection, IL-2 and GM-CSF were detected at higher concentrations, but there was a significant reduction of stimulated mononuclear cell production of IL-8, IL-10, IL-12p40, TNF-α, MCP-1, and MIP-1b in ESRD without diabetes group than in control group." (PMID 31875015, 2019). "Furthermore, studies demonstrate that chronic treatment with a low TNF dose or local pancreatic expression of TNF in adult non-obese diabetic (NOD) mice, which is a model for diabetes, delayed spontaneous development of type I diabetes in these mice." (PMID 29751683, 2018). "The tumor necrosis factor-α-induced protein 8 (TNFAIP8) family was distinguished not long ago; they are generated after TNF-α stimulation and NF-κB actuation, and they could be the molecular connection among TNF-α-mediated signaling and diabetes." (PMID 28626770, 2017). "We conclude that TNF-α-308G/A gene polymorphism was significantly correlated with the change in the circulating TNF-α levels from baseline in response to 12 months of CPAP treatment in this revascularized Swedish CAD cohort, independent of age, sex, BMI, baseline AHI, ESS, and diabetes." (PMID 37629366, 2023). "Similarly, TNFα addition in bECs, but not in mEC, upregulated the expression of TNFRSF11B, whose increased serum levels have been found in patients with inflammatory pathologies such as diabetes or atherosclerosis." (PMID 36721025, 2023). "Anti–TNF-α alone did not delay the induction of anti–PD-L1–induced diabetes (median time = 18.5 days versus 14 days, P = 0.97), but neutralization of anti–IFN-γ alone trended toward a delay in the time to diabetes (median time = 35.5 days versus 14 days, P = 0.18)." (PMID 35925682, 2022). "In a study of SRP in periodontal patients with diabetes, it was reported that there was no change in HbA1c and serum biomarkers (hs-CRP, TNF-α, IL-6) during the 6-month follow-up period, regardless of whether SRP was performed and the severity of periodontal disease." (PMID 36140045, 2022).
diabetes (continued). "In an extension of these studies, it was observed that serum that contained TNF 75 U but not IL-1, IL-2, and IFN-γ (induced by OK-432 injection) when administered reduced the intensity of insulitis and inhibited the cumulative incidence of diabetes in NOD mice compared to the control." (PMID 28824543, 2017).
atherosclerosis (2,049 papers, 2005 to 2026). A disease characterized by the build-up of fatty material and calcium deposition in the arterial wall resulting in partial or complete occlusion of the arterial lumen. "In patients with cardiometabolic risk factors, high IL-6 and TNF-α levels are related to endothelial dysfunction and progression of atherosclerosis, resulting in an increased overall risk for cardiovascular disease." (PMID 41590667, 2026). "KEGG analysis demonstrated significant enrichment in AGE-RAGE signaling, TNF-mediated inflammation, and lipid-atherosclerosis pathways, while GAD mapping indicated associations with type 2 diabetes and atherosclerosis." (PMID 41898163, 2026). "Proinflammatory cytokines, such as TNF-α and IL-17, contribute to the acceleration of atherosclerosis, thereby increasing cardiovascular risk, while systemic immunosuppression enhances susceptibility to severe infections." (PMID 40777007, 2025). "KEGG enrichment results demonstrated that the common targets participate in pivotal AS-associated pathways, including the PI3K-Akt, Lipid and atherosclerosis, and TNF signaling pathways." (PMID 41424781, 2025). "Knockout of IKK2 in macrophages in a mouse model of atherosclerosis revealed a reduction of TNFα expression and strong loss of IL-10 in macrophages when challenged by LPS38." (PMID 40461478, 2025). "Anti-inflammatory properties, reduces proatherosclerotic cytokines (TNF-α, IL-1, IL-6), improves cholesterol efflux, and decreases the risk of atherosclerosis." (PMID 40376321, 2025). "Overexpression of NFIA decreased the circulation of inflammatory cytokines, including IL‐6 and TNF‐α, and promoted regression of atherosclerosis in apolipoprotein E‐deficient mice, possibly through the nuclear factor kappa B (NF‐κB) pathway." (PMID 40560736, 2025). "TNF-α, a pro-inflammatory cytokine, plays a central role in joint inflammation and is implicated in the pathogenesis of atherosclerosis." (PMID 40137170, 2025). "In macrophages, Nr4a1 deficiency increased TNFα production, along with other proinflammatory cytokines, exacerbating inflammation driven atherosclerosis." (PMID 40114913, 2025). "Numerous inflammation-associated biomarkers, especially TNF-α and interleukin-6, have been identified as inflammatory biomarkers for monitoring atherosclerosis and cardiovascular risk." (PMID 39941424, 2025). "IL-2 and TNF-α are key regulators of immune responses and have been implicated in atherosclerosis and CAD pathogenesis." (PMID 40265387, 2025). "KEGG analysis indicated that the DEGs were mainly associated with several pathways, including lipid and atherosclerosis (Mus musculus), and the TNF signaling pathway (Mus musculus), among others." (PMID 40458459, 2025). "TNFα and IL-6 in particular, are associated with diminishing nitric oxide production and endothelial dysfunction, both known precursor factors for atherosclerosis and CVDs." (PMID 40370477, 2025). "Other prominent pathways included lipid metabolism and atherosclerosis metabolism, NF‒κB signaling, TNF signaling, and IL‒17 signaling, which are closely associated with chronic inflammation and immune dysregulation." (PMID 41287052, 2025). "At the molecular level, elevated levels of IL-6 and TNF-α have been linked to the progression of atherosclerosis and plaque instability, key precursors to MI." (PMID 39812546, 2025). "TNF-α is reported in the edges of the inflammatory lesions, so that atherosclerosis diminished in the apoE-deficient mice with the disrupted TNF-α." (PMID 40823653, 2025). "Specifically, in hypertensive and prehypertensive patients, inflammatory responses (such as increased levels of IL-6 and TNF-α) are closely associated with the progression of atherosclerosis." (PMID 40034990, 2025). "These included pathways associated with lipid metabolism, atherosclerosis, the IL‐17 signaling pathway, and the TNF signaling pathway." (PMID 41383581, 2025).